POU4F1 (POU class 4 homeobox 1)
Description:
Multifunctional transcription factor with different regions mediating its different effects. Acts by binding (via its C-terminal domain) to sequences related to the consensus octamer motif 5'-ATGCAAAT-3' in the regulatory regions of its target genes. Regulates the expression of specific genes involved in differentiation and survival within a subset of neuronal lineages. It has been shown that activation of some of these genes requires its N-terminal domain, maybe through a neuronal-specific cofactor. Activates BCL2 expression and protects neuronal cells from apoptosis (via the N-terminal domain). Induces neuronal process outgrowth and the coordinate expression of genes encoding synaptic proteins. Exerts its major developmental effects in somatosensory neurons and in brainstem nuclei involved in motor control. Stimulates the binding affinity of the nuclear estrogene receptor ESR1 to DNA estrogen response element (ERE), and hence modulates ESR1-induced transcriptional activity. May positively regulate POU4F2 and POU4F3. Regulates dorsal root ganglion sensory neuron specification and axonal projection into the spinal cord. Plays a role in TNFSF11-mediated terminal osteoclast differentiation. Negatively regulates its own expression interacting directly with a highly conserved autoregulatory domain surrounding the transcription initiation site. [Isoform 2]: Able to act as transcription factor, cannot regulate the expression of the same subset of genes than isoform 1. Does not have antiapoptotic effect on neuronal cells.
Synonyms: Brn-3A; BRN3A; RDC-1; ATITHS; Oct-T1
Tractability: No criterion of Open Targets' tractability assessment is met for any kind of drug.
Gene: Protein-coding gene on chromosome 13 (78,598,362 to 78,603,552, reverse strand). Ensembl gene ENSG00000152192.
Subcellular location: Nucleus; Cytoplasm
Gene Ontology:
Molecular function: DNA-binding transcription factor activity, RNA polymerase II-specific; protein binding; sequence-specific double-stranded DNA binding; DNA-binding transcription activator activity, RNA polymerase II-specific; DNA-binding transcription repressor activity, RNA polymerase II-specific; RNA polymerase II cis-regulatory region sequence-specific DNA binding; sequence-specific DNA binding; single-stranded DNA binding; chromatin binding; DNA binding; DNA-binding transcription factor activity; GTPase binding; RNA polymerase II-specific DNA-binding transcription factor binding
Biological process: axonogenesis; cellular response to cytokine stimulus; cellular response to estradiol stimulus; heart development; innervation; negative regulation of apoptotic process; negative regulation of gene expression; negative regulation of neuron apoptotic process; negative regulation of programmed cell death; negative regulation of transcription by RNA polymerase II; neuron fate specification; neuron projection development; peripheral nervous system neuron development; positive regulation of gene expression; positive regulation of osteoclast differentiation; positive regulation of transcription by RNA polymerase II; positive regulation of transcription regulatory region DNA binding; regulation of cell cycle; regulation of transcription by RNA polymerase II; sensory system development; synapse assembly; trigeminal nerve development; regulation of DNA-templated transcription; ventricular compact myocardium morphogenesis
Cellular component: nucleus; chromatin; cytoplasm; nucleoplasm; RNA polymerase II transcription regulator complex; neuron projection
Genetic constraint (gnomAD): Loss-of-function variants: 5 observed, 14.75 expected, observed/expected ratio (o/e) 0.34, 90% interval 0.18 to 0.71. The synonymous counts are far from expectation, so gnomAD's model fits this gene poorly and the ratio says little. Missense variants: 333 observed, 393.57 expected, observed/expected ratio (o/e) 0.85, 90% interval 0.77 to 0.93. Synonymous variants: 222 observed, 178.99 expected, observed/expected ratio (o/e) 1.24, 90% interval 1.11 to 1.39.
Homologues: Orthologues: dog POU4F1 (99% identical), mouse Pou4f1 (99% identical), macaque POU4F1 (99% identical), pig POU4F1 (99% identical), rat Pou4f1 (99% identical), chimpanzee POU4F1 (84% identical), tropical clawed frog pou4f1 (78% identical), rabbit POU4F1 (74% identical), zebrafish pou4f1 (74% identical), Drosophila melanogaster acj6 (48% identical), Caenorhabditis elegans unc-86 (36% identical). Paralogues in human: POU4F2 (60% identical), POU4F3 (59% identical), POU3F3 (26% identical), POU3F4 (25% identical), POU2F1 (25% identical), POU3F2 (25% identical), POU2F2 (25% identical), POU2F3 (24% identical), POU3F1 (23% identical), POU6F2 (23% identical), POU1F1 (23% identical), POU6F1 (23% identical), and 5 more.
Diseases named in the same sentence as POU4F1 in open-access papers:
POU4F1 is named in the same sentence as 68 diseases in open-access papers, as found by Europe PMC text mining. Sharing a sentence is not in itself a finding about the gene and the disease. The quoted sentences say what the papers report.
melanoma (16 papers, 2013 to 2024). A malignant, usually aggressive tumor composed of atypical, neoplastic melanocytes. "POU4F1 is a stem cell-associated transcriptional factor that is highly expressed in melanoma cells and contributes to BRAF-activated malignant transformation." (PMID 32532957, 2020). "In melanoma, POU4F1 is also able to promote acquired resistance to vemurafenib through paradoxical re-activation of MEK/ERK." (PMID 38539548, 2024). "Recently, it has been reported that POU4F1 enhance the proliferation and drug resistance of melanoma." (PMID 36176299, 2022). "Overexpression of the transcription factor POU4F1 (POU Class 4 Homeobox 1) contributed to the resistance to BRAFi in vemurafenib-treated melanoma cells by increasing MEK expression and activating MEK/ERK signaling." (PMID 34063141, 2021). "Our study supports that POU4F1 is a potential combined therapeutic target with BRAFi therapy for melanoma." (PMID 32532957, 2020). "High expression of POU4F1 was also observed at both mRNA level and protein level in melanoma tissues compared with nevus tissues." (PMID 32532957, 2020). "Our study provides the evidence for the contribution of POU4F1 to the resistance of melanoma cells to BRAFi via activating MEK/ERK pathway and MITF." (PMID 32532957, 2020). "In order to explore the potential role of POU4F1 in the resistance of melanoma to BRAFi, we first performed POU4F1 expression analysis using data from the GEO database." (PMID 32532957, 2020). "Based on these previous findings, the current preclinical study was undertaken to explore the role of POU4F1 in the formation of BRAFi resistance in melanoma as well as the molecular mechanism involved in the process." (PMID 32532957, 2020). "Here, we report that over-expressed POU4F1 contributed to the acquired resistance of melanoma cells to Vemurafenib." (PMID 32532957, 2020). "The data showed that POU4F1 expression in melanoma tissues increased significantly after the occurrence of resistance to dabrafenib (P = 0.0357)." (PMID 32532957, 2020). "To further confirm the oncogenic role of POU4F1 in melanoma, we analyzed the expression levels of POU4F1 and Ki-67 in nevus tissues and melanoma tissues from different progression stages." (PMID 32532957, 2020). "This parallel change of Ki-67 and POU4F1 expressions demonstrates that POU4F1 is a potential biomarker for determining the status of melanoma patients." (PMID 32532957, 2020). "To test the function of POU4F1 in BRAFi resistance, we established two melanoma cell lines (A2058 and 451Lu) with acquired resistance to Vemurafenib." (PMID 32532957, 2020). "In conclusion, our study demonstrates that POU4F1 is up-regulated in the melanoma cells, which promotes the resistance to BRAFi by the activation of MEK/ERK pathway and MITF." (PMID 32532957, 2020). "Most melanoma cell lines (7/10, 70%) expressed high mRNA level of POU4F1 compared with NHMs or PIG1 cells that are an immortalized melanocytic cell line." (PMID 32532957, 2020). "What is interesting about these two genes, both of which are overexpressed in melanoma cell lines, is that an up-regulated BRN2 can participate in the de-differentiation of human melanocytes, and POU4F1 appears to have a critical role in melanoma development." (PMID 27149382, 2016). "Consistently, POU4F1 was increased in most melanoma cell lines at protein level." (PMID 32532957, 2020). "Targeting POU4F1 may be a potential therapeutic approach combined with BRAFi for the therapy of melanoma in the future." (PMID 32532957, 2020). "Moreover, PD98059 suppressed the effect of POU4F1 overexpression on the resistance of melanoma cells to Vemurafenib." (PMID 32532957, 2020). "In addition, our CCK8 and colony formation assays showed that blocking either the expression of POU4F1 by shRNA or the activation of MEK/ERK pathway by PD98059 restored the sensitivity of melanoma cells to Vemurafenib." (PMID 32532957, 2020).
melanoma (continued). "In addition, POU4F1 could increase the expression of MITF to retain the resistance of melanoma cells to BRAFi." (PMID 32532957, 2020). "However, whether POU4F1 contributes to the resistance of melanoma to BRAFi remains poorly understood." (PMID 32532957, 2020). "As a transcription factor, POU4F1 has been shown to transcribe and regulate the expression of MEK in melanoma, thereby reactivating the MAPK pathway and leading to resistance against BRAF inhibitors." (PMID 38962013, 2024). "We found that POU4F1 and MITF were parallelly increased in Vemurafenib-resistant melanoma cells compared with parental cells." (PMID 32532957, 2020). "Therefore, POU4F1 may be involved in the resistance of melanoma to BRAFi." (PMID 32532957, 2020). "Subsequent immunoblot assay showed that the expression of MITF was increased in melanoma cells with POU4F1 overexpression and decreased in melanoma cells with POU4F1 knockdown, proving that the expression of MITF was regulated by POU4F1." (PMID 32532957, 2020). "Collectively, our findings reveal that POU4F1 re-activates the MAPK pathway by transcriptional regulation on MEK expression and promotes MITF expression, which ultimately results in the resistance to BRAFi in melanoma." (PMID 32532957, 2020). "We performed immunohistochemistry to evaluate both POU4F1 and Ki-67 expression scores in tissue specimens from 20 melanoma cases as well as 6 noncancerous nevus cases." (PMID 32532957, 2020). "POU4F1 expression was analyzed in human melanoma cell lines and non-malignant melanocytes." (PMID 32532957, 2020). "However, both the CCK8 and colony formation assays showed significantly higher cell growth in POU4F1-overexpressed melanoma cells under the treatment of PD98059, indicating that MEK/ERK is not the only downstream effecter of POU4F1 in the formation of BRAFi resistance in melanoma." (PMID 32532957, 2020). "Supplementary to these previous findings, our study found that elevated POU4F1 could activate MEK/ERK that is a key link in the whole MAPK pathway, thus leading to the resistance to BRAFi in melanoma cells, which is a novel mechanism for MAPK pathway reactivation in melanoma under BRAFi treatment." (PMID 32532957, 2020).
glaucoma (10 papers, 2015 to 2025). Increased pressure in the eyeball due to obstruction of the outflow of aqueous humor. "Since glaucoma is defined as an optic neuropathy due to degeneration of RGC axons, we focused on RGC development by looking at transcriptional activation of pou4f1 (also known as brn3a) which is expressed early in post-mitotic RGC precursors and plays an important role in their development." (PMID 36148008, 2022).
renal fibrosis (7 papers, 2021 to 2025). A final common manifestation of a wide variety of chronic kidney diseases characterized by glomerulosclerosis and tubulointerstitial fibrosis. "A research team from The Chinese University of Hong Kong discovered that hyperactivated macrophages can transdifferentiate into myofibroblasts to accelerate renal fibrosis, a process driven by aberrant expression of the neuronal gene Pou4f1." (PMID 40959285, 2025). "Recently, Pou4f1 was found to be expressed in kidney infiltrating macrophages in progressive renal fibrosis, with the proportion of Pou4f1+ macrophages being correlated with the degree of macrophage–myofibroblast transition in human kidney tissues." (PMID 38218914, 2024). "Proto-oncogene tyrosine protein kinase Src and neural transcription factor Pou4f1 have been identified as key downstream regulators in the TGF-β1/Smad3 signaling for promoting renal fibrosis via macrophage-myofibroblast transition (MMT)." (PMID 34299192, 2021). "Targeting Pou4f1 in macrophages effectively prevents renal fibrosis." (PMID 40959285, 2025). "As a target of SMAD3, Pou4f1 leads to renal fibrosis by promoting MMT." (PMID 38961399, 2024). "Researchers determined that POU Class 4 Homeobox 1 (Pou4f1), a direct Smad3 target gene in the TGF-β1-induced MMT process in BMDMs, was a potential therapeutic target to prevent renal fibrosis." (PMID 35990655, 2022).
breast carcinoma (6 papers, 2021 to 2025). "When the mammary epithelial cells were transformed into BLBC, bivalent POU4F1 lost H3K27me3, resulting in gene activation, while in other breast cancer subtypes, bivalent POU4F1 lost H3K4me3, resulting in gene silence." (PMID 38491910, 2024). "Previous studies have identified POU4F1 as a factor that induces resistance to trastuzumab in breast cancer cells by mediating the ERK1/2 pathway." (PMID 38962013, 2024). "The bivalent gene POU4F1 is epigenetically activated in basal‐like breast cancer by DNA demethylase TET1." (PMID 38491910, 2024). "Similarly, in basal-like breast cancer, it enhances invasion through POU4F1 activation, promoting cell cycle progression and invasion, whereas TET1 inhibition reduces metastatic potential." (PMID 41165593, 2025). "Consistent with the online TCGA and METABRIC database, POU4F1 expression, determined by immunohistochemistry staining, was significantly higher in breast cancer tissues of TNBC patients, compared with ones of luminal A, luminal B and HER2‐positive breast cancer patients and normal breast tissues." (PMID 38491910, 2024). "To further investigate whether ectopic expression of POU4F1 may influence the phenotype of breast cancer, we stably expressed POU4F1 in the committed ER+ breast cancer cell lines, MCF7 and ZR751." (PMID 38491910, 2024). "However, other subtypes of breast cancer cell lines exhibited enhanced binding of H3K27me3 in POU4F1 promoter, indicating the repressed transcription of POU4F1, which was further validated by ChIP‐qPCR." (PMID 38491910, 2024). "Moreover, the inhibitory effect of estrogen deprivation on ER+ breast cancer cell growth was significantly reduced when POU4F1 was overexpressed." (PMID 38491910, 2024). "In breast cancer cells, through analyzing the public available ChIP‐seq dataset, we found that the chromatin at the POU4F1 promoter in BLBC cell lines was characterized by the increased binding of H3K4me3 and H3K27ac, representing POU4F1 promoter was open for active transcription in BLBC." (PMID 38491910, 2024). "Studies have shown that POU4F1 expression is dramatically increased in breast cancer cells." (PMID 34178671, 2021). "In addition, targeting POU4F1 may be a new effective treatment for trastuzumab (TRA) resistance in human HER2 positive breast cancer." (PMID 36176299, 2022). "Altogether, these data demonstrated that POU4F1 was required for BLBC cell identity and might contribute to the switch of lineage commitment in breast cancer cell lines." (PMID 38491910, 2024). "Moreover, we observed a significant negative correlation between POU4F1 expression and master transcription factors of ER positive breast cancer, such as ESR1, FOXA1 and GATA3, in breast cancer patients from the TCGA and METABRIC cohorts." (PMID 38491910, 2024).
colorectal cancer (3 papers, 2022 to 2024). A primary or metastatic malignant neoplasm that affects the colon or rectum. "The expression of CCKBR, HOXC6, and POU4F1 were significantly higher in colorectal cancer cell lines compared to those in FHC cells." (PMID 36176299, 2022). "Several studies suggest that POU4F1 may be a hub gene in certain signature of colorectal cancer, yet its specific role has not been experimentally validated." (PMID 39749343, 2024).
leukemia (3 papers, 2010 to 2023). A malignant (clonal) hematologic disorder, involving hematopoietic stem cells and characterized by the presence of primitive or atypical myeloid or lymphoid cells in the bone marrow and the blood. "Furthermore, the TF POU4F1 is known to be overexpressed in RUNX1/RUNX1T1 leukemia." (PMID 36980682, 2023).
acute myeloid leukaemia (2 papers, 2014 to 2023). "In the present study, POU4F1, which paired with miR-150-5p, was a neuro transcription factor that was closely related to AML1/ETO gene fusion in acute myeloid leukemia." (PMID 37745305, 2023).
Ataxia (2 papers, 2025 to 2026). Ataxia refers to impaired coordination of voluntary muscle movement. "It is proposed that the heterozygous loss-of-function (LOF) variant in POU4F1 is the causative agent of this novel ataxia syndrome." (PMID 41158507, 2025). "This is the first reported case of a nonsense variant of POU4F1 associated with this ataxia syndrome." (PMID 41158507, 2025). "We have described a novel neurodevelopmental disorder caused by de novo, heterozygous pathogenic variants in the Pou domain, class 4, transcription factor 1 (POU4F1), now termed ataxia, intention tremor, and hypotonia syndrome, childhood-onset (ATITHS)." (PMID 41723941, 2026). "It reported four independent patients with ataxia, intention tremor, and hypotonia, identified 4 de novo, heterozygous, LOF variants in POU4F1." (PMID 41158507, 2025).
glioma (2 papers, 2024). A benign or malignant brain and spinal cord tumor that arises from glial cells (astrocytes, oligodendrocytes, ependymal cells). "This traditional preparation promotes the pyroptosis of glioma cells via the POU4F1/STAT3 axis and effectively halts glioma proliferation, although its precise mechanisms and clinical applicability warrant further investigation." (PMID 39184045, 2024). "Studies have shown that in primary glioma models (U251 and SHG-44), XHP treatment alone downregulated POU4F1 and STAT3 levels and increased LDH release and IL-1β and IL-18 levels, and the apoptosis-associated factor NLRP3 was activated." (PMID 38957318, 2024). "XHP promotes cellular pyroptosis by regulating the POU4F1/STAT3/NLRP3 pathway and inhibits glioma malignant progression." (PMID 38957318, 2024).
Intention tremor (2 papers, 2025 to 2026). A type of kinetic tremor that occurs during target directed movement is called intention tremor. "Beyond its ocular role, POU4F1 has mainly been associated with neurological manifestations, including childhood-onset ataxia, intention tremor, and axial hypotonia." (PMID 40978814, 2025).
ovarian carcinoma (2 papers, 2010 to 2024). A malignant neoplasm originating from the surface ovarian epithelium. "Another study unveiled the correlation between the elevated expression of neuronal transcription factor Brn-3a (POU4F1) and the decreased rate of apoptosis in ovarian cancer cells." (PMID 39456618, 2024).
squamous cell carcinoma of the cervix (2 papers, 2009 to 2021). "POU4F1 as a cellular transactivator was shown to be expressed at elevated levels in squamous cell carcinoma of the cervix and to activate the expression of HPV E6 mRNA." (PMID 34970597, 2021).
Alzheimer disease (1 paper, 2020). A progressive, neurodegenerative disease characterized by loss of function and death of nerve cells in several areas of the brain leading to loss of cognitive function such as memory and language. "This would be the case of genes such as POU4F1 for Alzheimer's disease or CLC for schizophrenia." (PMID 32392208, 2020).